NLRP3 (NLR family pyrin domain containing 3)
Diseases named in the same sentence as NLRP3 in open-access papers (continued):
Sharing a sentence is not in itself a finding about the gene and the disease.
Sepsis (continued). "Taken together, our study propose autophagy-NLRP3 axis is a new pathway in endothelial injury of sepsis, which deserves further investigation." (PMID 34011327, 2021). "Taken together, all these data reinforce the idea that NLRP3 plays a crucial role in inflammation induced muscle atrophy in sepsis." (PMID 34831246, 2021). "Our results support that GPR43 is involved in the activation of NLRP3 inflammasome in macrophage of sepsis through the regulation of mitochondrial fission." (PMID 34584017, 2021). "In sepsis mice and LPS-induced macrophages, autophagy-induced inactivation of the NLRP3 inflammasome can reduce the release of proinflammatory cytokines." (PMID 34220338, 2021). "This study identified a possible signal pathway that activated NLRP3 Inflammasome to secrete IL-1β levels under sepsis conditions." (PMID 34584017, 2021). "In this study, EBP50/Nox1/p47phox is involved in the activation of NLRP3 Inflammasome in sepsis model by the inhibition of GPR43 via PPARγ." (PMID 34584017, 2021). "Together with previous findings, our results indicate that GRP43 alleviated mitochondrial damage in macrophage by the promotion of ROS production to alleviate NLRP3 inflammasome of sepsis model by PPARγ/ Nox1/ EBP50/p47phox signaling." (PMID 34584017, 2021). "In particular, the NLRP3 inhibitor MCC950 attenuates multi-organ injuries in septic rats, highlighting the potential of using NLRP3 inhibitors in the treatment of sepsis." (PMID 33796108, 2021). "The study revealed that upon LPS priming, ABRO1 binds to NLRP3 and recruits BRISC to promote K63-dependent deubiquitination of NLRP3 and that a deficiency of BRCC3/ABRO1 attenuates NLRP3-associated inflammatory diseases such as peritonitis or sepsis." (PMID 34445484, 2021). "Overall, these results revealed that SESN2 suppresses CHOP-mediated activation of NLRP3/CASP-1-dependent pyroptosis during sepsis." (PMID 34741186, 2021). "Third, the regulatory relationship between LBH and NLRP3 inflammasome on inflammatory responses in sepsis-induced ALI is limited to the cellular level and in vivo experiments are needed." (PMID 33553423, 2021). "Next, through screening, we found that SARS-CoV-2 N protein promoted the expression of inflammatory factors by activating NLRP3 inflammasome, resulting in mouse lung injury and exacerbating the death of mice in the sepsis model." (PMID 34341353, 2021). "For instances, hemin alleviates sepsis-induced ALI by inhibiting activation of NLRP3 inflammasome and attenuating inflammatory response in vitro." (PMID 33553423, 2021). "In PINK1–PARK2 gene knockout mice, a decrease in the circulating level of the neurotransmitter dopamine has been observed, as well as activation of NLRP3 inflammasome and overexpression of downstream sepsis mediator, HMGB1." (PMID 34257519, 2021). "Intraperitoneal injection of lipopolysaccharide induces sepsis, and the activation of the NLRP3 inflammasome plays a crucial role in vivo, accompanied by the production of IL-1β and the occurrence of inflammation." (PMID 34721038, 2021). "Consistently, our data showed that sepsis patients exhibited significantly higher NLRP3 gene expression and protein production than healthy volunteers, and these levels were also increased with disease severity." (PMID 34172780, 2021). "Our experiments suggest that LPS and IL-38 exert at least some of their effects in sepsis by influencing the NLRP3 inflammasome." (PMID 34955683, 2021). "Many studies have reported that the NLRP3 inflammasome is involved in HMGB1 elevation in sepsis, inflammatory kidney disease, acute lung injury, and other infectious diseases, and most studies have focused on immune cells such as macrophages and microglia." (PMID 34539383, 2021). "This is the case of acute lung injuries such as sepsis or pneumonia, in which melatonin has been reported to reduce lung inflammation by selectively inhibiting the assembly of the NLRP3 inflammasome." (PMID 34356384, 2021).
Sepsis (continued). "Targeting NLRP3 inflammasome has been considered as a novel therapeutic approach for treating sepsis." (PMID 34207356, 2021). "The NLRP3 inflammasome enlarges inflammatory response, triggers apoptosis of immune cells, and aggravates the progress of sepsis." (PMID 34220338, 2021). "We investigated the mechanism of how GPR43 gene triggered NLRP3 Inflammasome in sepsis-induced inflammatory reactions." (PMID 34584017, 2021). "As shown by our results, NLRP3 inflammasome activity was triggered by GPR43 gene in sepsis-induced inflammatory reactions model." (PMID 34584017, 2021). "Autophagy activation demonstrated protective effect on sepsis-induced organ damage through NLRP3 inflammasome inactivation." (PMID 34011327, 2021). "Here, our data support the notion that the NLRP3 inflammasome is activated by LPS in cardiomyocytes to mediate pyroptosis for sepsis pathogenicity." (PMID 34873405, 2021). "To further explore the effects of LBH on lung injury, inflammatory responses, and NLRP3 inflammasome activation in sepsis-induced ALI, we performed in vivo experiments in sepsis-induced ALI mouse model." (PMID 33553423, 2021). "Dihydromyricetin alleviates inflammatory reactions by suppressing the CLP-induced NLRP3 inflammasome pathway in sepsis-induced ALI." (PMID 33553423, 2021). "In short, mitochondrial damage caused by ROS production represented a general mechanism that GPR43 induced NLRP3 Inflammasome activity in sepsis-induced inflammatory reactions model." (PMID 34584017, 2021). "To explore the effect of NLRP3 on the sepsis-induced inflammatory response, we detected NLRP3 expression in LPS-stimulated macrophages." (PMID 34220338, 2021). "To conclude, GPR43 is involved in the inactivation of NLRP3 inflammasome in sepsis model by ROS-induced mitochondrial damage via PPARγ/ EBP50/Nox1/p47phox." (PMID 34584017, 2021). "We show that inhibition of the NLRP3/IL‐1β axis protects against systolic and diastolic dysfunction in sepsis." (PMID 34472725, 2021). "NLRP3 inflammasome inhibition attenuates sepsis-induced multiorgan injury in cecal ligation puncture (CLP)." (PMID 34220338, 2021). "These events hamper the binding of pro-caspase-1 to ASC, inhibiting NLRP3 inflammasome activation and alleviating LPS-induced sepsis injury in mice." (PMID 34305952, 2021). "Previous studies demonstrated that the α2 receptor agonist DEX was relieved by blocking the first signal of the activation of NLRP3 inflammasome in sepsis and acute kidney injury." (PMID 34079457, 2021). "This experiment analyzed the GPR43 regulated NLRP3 inflammation and associated inflammation, however, we will further research GPR43 affect apoptosis and pyrocytosis in sepsis by the regulation of NLRP3 inflammasome." (PMID 34584017, 2021). "Together with previous findings, our results indicate that GPR43 suppressed NLRP3 inflammasome through the inhibition of ROS production-induced mitochondrial fission in macrophage of sepsis." (PMID 34584017, 2021). "Being a part of the innate immune system, the NLRP3 inflammasome contributes to the response against sepsis, sometimes with deleterious effects." (PMID 34202842, 2021). "We previously demonstrated NOD-like receptor protein 3 inflammasome (NLRP3) inflammasome activation in sepsis-induced platelets from cecal-ligation puncture (CLP) rats." (PMID 34638670, 2021). "Here, we show that cardiac function and structure deteriorates during sepsis and that inhibition of NLRP3/IL‐1β improves both entities." (PMID 34472725, 2021). "Nucleotide-binding domain and leucine-rich repeat (LRR)-containing family protein 3 (NLRP3) regulated the maturation of inflammation-related cytokines by forming NLRP3 inflammasome, which plays pivotal roles in sepsis pathogenesis." (PMID 34172780, 2021). "In our previous study, we have found that dihydromyricetin ameliorates sepsis-stimulated acute lung injury through blocking NLRP3/caspase-1 signaling in mice models." (PMID 34992715, 2021).
Sepsis (continued). "NLRP3 knockout mice are incapable of activating IL-1β and therefore show reduced IL-1β serum levels at baseline as well as in sepsis." (PMID 34572540, 2021). "Our data indicate that Nlrp3 deletion protects from cardiac atrophy and systolic and diastolic dysfunction during sepsis." (PMID 34472725, 2021). "It has been reported that another member of the S100 family, S100A12, promotes sepsis-induced ARDS via activating the NLRP3 pathway." (PMID 33549095, 2021). "The NLRP3 regulatory effects of artemisinin were also demonstrated in a murine model of burn sepsis." (PMID 34443594, 2021). "In summary, we propose that SESN2 impedes NLRP3–ASC–CASP-1-mediated pyroptosis by preserving ER homeostasis during sepsis." (PMID 34741186, 2021). "There are five inflammasomes, of which the NLRP3 inflammasome plays a key role in sepsis and multiple organ dysfunction as an important component of innate immunity." (PMID 34745104, 2021). "This study provides new insight into the role of CstC in LPS-induced sepsis and NLRP3 inflammasome activation." (PMID 34440840, 2021). "A recent study reported that the complement system activates the cardiac NLRP3 inflammasome in CLP‐induced sepsis mediating cardiomyopathy and Nlrp3 deletion was shown to be cardioprotective, which is in line with our data." (PMID 34472725, 2021). "Reactive oxygen species interactions with NLRP3 inflammasomes participate in regulating the immune inflammation responses during sepsis." (PMID 33324236, 2020). "Reactive oxygen species destroy mitochondrial integrity, promote cell apoptosis, and aggravate the inflammatory responses by promoting NLRP3 inflammasome activation in sepsis." (PMID 33324236, 2020). "Baicalin decreases NLRP3 inflammasome activation to improve survival in sepsis mice by augmenting protein kinase A signaling." (PMID 33324236, 2020). "Sepsis/endotoxemia activates the NLRP3 inflammasome of macrophages leading to the maturation and release of IL-1β, an important mediator of the inflammatory response." (PMID 33101273, 2020). "MCC950 is a well characterized specific inhibitor of NLRP3, and very few studies have examined in a role for this NLRP3 specific inhibitor to protect against sepsis induced multi-organ injury in a prolonged model of sepsis." (PMID 32555710, 2020). "A previous study has shown that mesenchymal stromal cells have beneficial effects on systemic inflammation during sepsis through mitophagy activation and suppression of mitochondrial ROS and the NLRP3 inflammasome in macrophages." (PMID 32630319, 2020). "Recently, many studies have confirmed that NLRP3 inflammasome was activated in sepsis-induced multiple organ injury." (PMID 33178042, 2020). "Inhibition of NLRP3 inflammasomes has shown great benefit for inflammation control and life extension in sepsis mice." (PMID 33324236, 2020). "NLRP3 inflammasomes enlarge the inflammatory response and trigger apoptosis of immune cells to exacerbate sepsis progression." (PMID 33324236, 2020). "The findings of this study showed that pretreatment with GLN increased liver caspase-11 and NLRP3 gene expressions at 24 h, while caspase-1/11 and GadD protein levels were downregulated at 72 h after sepsis." (PMID 32295272, 2020). "By contrast, NLRP3 and IL-1R1 are required for long-term maintenance of microglial activation after sepsis." (PMID 32070376, 2020). "studies is that, our data suggests that NLRP3 is not only a potential therapeutic target for early intervention in sepsis, but also late intervention." (PMID 32555710, 2020). "A feed-forward mechanism for IL-1β generation exists, i.e., IL-1β can activate the NLRP3 inflammasome and vice versa, representing a potential mechanism of generating the exaggerated cytokine response in sepsis." (PMID 33101273, 2020). "In this review, we mainly focused on the interaction of ROS and NLRP3 inflammasomes during sepsis, to describe the mechanism of inflammation as well as the progress in therapies." (PMID 33324236, 2020).
Sepsis (continued). "Autophagy has a protective role in some inflammatory diseases associated with NLRP3 inflammasome, including gouty arthritis, familial Mediterranean fever (FMF), and sepsis." (PMID 33163006, 2020). "The Sepsis-G group had higher caspase-11 and NLRP3 expressions than the Sepsis-C group by 24 h post-CLP." (PMID 32295272, 2020). "Wet/Dry ratio significantly decreased in CLP+MCC950 to 3.5±0.4, indicating that NLRP3 inhibition improves pulmonary edema in the CLP sepsis model (p<005)." (PMID 32555710, 2020). "Compared to the Sepsis-C group, the Sepsis-G group had higher liver caspase-11 and NLRP3 gene expressions at 24 h and lower active caspase-1/11 and cleaved GadD protein levels at 72 h after sepsis." (PMID 32295272, 2020). "Complexing the matter of inflammaging is the observation that aged individuals have higher rates of sepsis incidence and mortality, resulting from the inability to launch an effective NLRP3 inflammasome response to infection." (PMID 32751530, 2020). "Drugs designed to target NLRP3 inflammasome activation show promise in treating NLRP3-dependent inflammatory diseases including sepsis in animal models." (PMID 32648582, 2020). "Cumulative evidences showed that the activation of NLRP3 inflammasome played a key role in sepsis-induced myocardial injury." (PMID 33178042, 2020). "In this section, we confirmed that the protective estrogen against sepsis-induced liver damage in mice was through suppressing NLRP3-mediated the activation of pyroptosis signaling pathway." (PMID 33002070, 2020). "Our results demonstrate a role for NLRP3 in contributing to platelet activation and multi-organ injury in sepsis." (PMID 32555710, 2020). "In this study, we found that Ethyl pyruvate treatment significantly attenuated cognitive decline, microglia activation, and impaired neurogenesis in experimental sepsis, at least in part, through inhibition of the NLRP3 inflammasome.." (PMID 32517686, 2020). "Both sepsis groups had higher gene expressions of NLRP3, caspase-11, and IL-1β and lower expression of IL-18 compared to the sham group." (PMID 32295272, 2020). "Other studies have demonstrated a role for NLRP3 in lung injury induced by sepsis, mechanical ventilation, hyperoxia, burns, bleomycin, acid aspiration, and primary graft dysfunction after lung transplantation." (PMID 33128438, 2020). "The ability of the NLRP3 inhibitor to decrease platelet activation identifies a novel mechanism of sepsis progression." (PMID 32555710, 2020). "The mtDNA serves as a viable plasma biomarker for critically ill patients, and activates NLRP3 to trigger cytokine release and exacerbate the inflammatory response of sepsis." (PMID 33324236, 2020). "Genetic or pharmacological inhibition of NLRP3 improves survival during polymicrobial sepsis or E. coli infection in mice." (PMID 32751530, 2020). "NLRP3 activation is linked to a number of inflammatory conditions, including sepsis and several studies have shown that NLRP3 null animals are protected against sepsis induced organ injury and shock." (PMID 32555710, 2020). "Sulfur dioxide attenuates sepsis-induced cardiac dysfunction by inhibiting inflammation via the TLR4/NLRP3 signaling pathway." (PMID 33324236, 2020). "In a study, mesenchymal stromal cells showed beneficial effects on experimental sepsis through the inhibition of macrophage NLRP3 inflammasome activation via suppression of mtROS." (PMID 32922385, 2020). "It has been reported that extracellular histones can activate nucleotide-binding oligomerization domain-like receptor protein 3 (NLRP3) inflammasome, but its mechanism in sepsis pyroptosis is incompletely clear." (PMID 32432055, 2020). "In earlier studies, we demonstrated increased NLRP3 and IL-1β expression in cardiomyocytes during sepsis in mice and substantial release of IL-1β from cardiomyocytes in presence of LPS and ATP or nigericin." (PMID 32410859, 2020).
Sepsis (continued). "A number of previous studies have demonstrated that inhibition of NLRP3 protects against sepsis-induced organ injury." (PMID 32555710, 2020). "Although ROS and NLRP3/caspase-1-induced apoptosis in sepsis have been studied, future experiments are needed to show more evidence for their cooperation or interaction." (PMID 33324236, 2020). "The protective effects of NAC in sepsis results from its inhibition of NF-κB activation, which is an essential priming step for NLRP3 inflammasome activation." (PMID 33324236, 2020). "The activation of the NLRP3 inflammasome during sepsis is related to mitochondrial dysfunction and organ injury." (PMID 33182702, 2020). "IL-1β and IL-18 are crucial activation elements of the NLRP3 inflammasome during pyroptosis, and their production is known to be activated by I/R and sepsis but suppressed by propofol." (PMID 33260147, 2020). "A recent study reported that SESN2 suppressed sepsis by inhibiting NLRP3 activation and inducing autophagy in macrophages." (PMID 32155890, 2020). "In this review, we describe the interaction of ROS and NLRP3 inflammasomes during sepsis, provide prevention strategies, and identify fields that need further study." (PMID 33324236, 2020). "Changes in plasma NO and renal NLRP3 inflammasome-related protein expression were abrogated when L-NIL was given to the Arg sepsis groups." (PMID 32454788, 2020). "Inactivation of the NLRP3 inflammasome by the manipulation of metabolic pathways, including glucose and cholesterol metabolism, also protects mice from sepsis." (PMID 32751530, 2020). "In the present study, we have provided evidence to support a role for a peroxynitrite/PKR pathway in the regulation of NLRP3 inflammasome pathway in cardiac fibroblasts with relevance to endotoxemia/sepsis." (PMID 33101273, 2020). "A prominent intracellular PRR in sepsis is the NLRP3 (NOD-like, leucine rich repeat domains, and pyrin domain-containing protein 3)." (PMID 33101273, 2020). "This study suggests that TXNIP/NLRP3 signaling is critical for the pathogenesis of sepsis-induced myocardial damage." (PMID 32751530, 2020). "NLRP3 represents one of the most comprehensively characterized inflammasomes that was shown to be involved in diverse conditions such as sepsis, infectious diseases, and auto-inflammatory diseases." (PMID 32714974, 2020). "Recent studies proved that NLRP3 inflammasome triggered the cardiomyopathy of polymicrobial sepsis induced by cecal ligation and puncture." (PMID 31121492, 2019). "Nlrp3−/− neutrophils show decreased autophagy and augmented phagocytosis leading to survival in polymicrobial sepsis, indicating pleiotropic effects of neutrophil regulation under NLRP3 inflammasome signaling." (PMID 31270454, 2019). "This study highlighted the protective effect of SESN2 from sepsis and sepsis shock by maintaining mitophagy activation to inhibit NLRP3 inflammasome hyperactivation for immunological homeostasis." (PMID 31867002, 2019). "On the other hand, the emerging role of TLR4 and NLRP3 activation in inflammatory and autoimmune diseases, such as sepsis and lupus, among others has suggested the use of TLR4 and NLRP3 antagonists in therapy." (PMID 31062071, 2019). "In this study, we used a rat model of chronic sepsis induced by CLP to determine if NLRP3 is activated in platelets in response to sepsis." (PMID 31054188, 2019). "Previous studies have shown that resveratrol can suppress NLRP3 and subsequent IL-1β in sepsis models." (PMID 30691208, 2019). "We used the CLP rat model to investigate NLRP3 assembly and activation in platelets in response to in vivo sepsis." (PMID 31054188, 2019). "Caspase 1 activity and secretion of IL‐1β by platelets were assessed to confirm activation of the NLRP3 inflammasome in platelets after induction of sepsis in CLP rats." (PMID 31054188, 2019).